YWHAZ (tyrosine 3-monooxygenase/tryptophan 5-monooxygenase activation protein zeta)
Diseases named in the same sentence as YWHAZ in open-access papers (continued):
Sharing a sentence is not in itself a finding about the gene and the disease.
glioma (3 papers, 2021 to 2022). A benign or malignant brain and spinal cord tumor that arises from glial cells (astrocytes, oligodendrocytes, ependymal cells). "Previous studies demonstrated that YWHAZ could promote glioma cell invasion by activating the PI3K/AKT pathway." (PMID 34195070, 2021).
Insulin resistance (3 papers, 2019 to 2024). Increased resistance towards insulin, that is, diminished effectiveness of insulin in reducing blood glucose levels. "Additionally, genetic alterations in these genes are strongly involved, especially mutations in five genes (DGAT1, FASN, LPL, IRS2, and YWHAZ), in lipid synthesis, insulin resistance, and cancer progression." (PMID 31717414, 2019).
laryngeal carcinoma (3 papers, 2014 to 2023). Carcinoma that arises from the laryngeal epithelium. "Considerable proteins, such as YWHAZ, S100-A11, glutathione S-transferase, alpha-enolase, flavin reductase, fascin, and carbonic anhydrase, have been reported to be associated with laryngeal carcinoma in previous proteomics studies but without clinical validation and in-depth functional research." (PMID 24587265, 2014). "We choose cutoff 1200 for degree and therefore YWHAZ and PPP2R1A as the toptwo up-regulated genes and also HSP90AA1 and CALM3 as the top two down-regulated genes areintroduced as human laryngeal cancer." (PMID 29755572, 2018). "Finally, a possible biomarker panelincluding YWHAZ and PPP2R1A as the two up-regulated genes and HSP90AA1 and CALM3 as the twodown-regulated genes for human laryngeal cancer is introduced." (PMID 29755572, 2018).
adenoma (2 papers, 2021 to 2022). A neoplasm arising from the epithelium. "The univariable analyses performed on a well-characterized cohort (the Swedish Watchful Waiting Cohort after TURP or adenoma enucleation), revealed a positive association of increased expression of APOE, YWHAZ, and NDRG1 with poor OS." (PMID 33483585, 2021).
Arthritis (2 papers, 2024). Inflammation of a joint. "Overall, intellectual disability and arthritis emerged as a common phenotypic theme associated with YWHAZ and its pseudogene-harboring chromosomal bands." (PMID 38674334, 2024). "14-3-3zeta (YWHAZ) protein was shown to have a suppressive activity in arthritis in rats, and its deletion increased disease severity." (PMID 38726004, 2024).
breast invasive carcinoma (2 papers, 2020 to 2025). "YWHAZ was significantly up-regulated in 15 types of tumors, such as breast invasive carcinoma and stomach adenocarcinoma, and significantly down-regulated in two types of tumors." (PMID 39403688, 2025). "To date, combinations of YWHAZ and several oncogenic molecules had been considered to promote transition to invasive breast cancer 38-40." (PMID 32127952, 2020).
cholangiocarcinoma (2 papers, 2022 to 2025). A carcinoma that arises from the intrahepatic biliary tree (intrahepatic cholangiocarcinoma) or from the junction, or adjacent to the junction, of the right and left hepatic ducts (hilar cholangiocarcinoma). "In HCC and mouse cholangiocarcinoma, MATα1 phosphorylation on S180 and T202 leads to its nuclear accumulation by interfering with YWHAZ interaction." (PMID 40141131, 2025).
E. coli infection (2 papers, 2019 to 2021). "The expression of six genes (KRT18, ARPC5L, ACTG1, ARPC2, EZR, and YWHAZ) related to pathogenic E. coli infection was simultaneously increased with TNFRSF11B overexpression via gene set enrichment analysis (GSEA)." (PMID 34938284, 2021). "In addition, only six genes (KRT18, ARPC5L, ACTG1, ARPC2, EZR, and YWHAZ) related to pathogenic E. coli infection were simultaneously increased in both GSEA studies; these genes are mostly involved in focal adhesion, as determined via GO analysis." (PMID 34938284, 2021). "TNFRSF11B may affect the transcriptional activity of YWHAZ to regulate pathogenic E. coli infection, which was further validated in the TCGA-COAD database, in which increased TNFRSF11B expression correlated with increased TWHAZ expression (cor = 0.185, p <0.001)." (PMID 34938284, 2021). "Enrichment analysis using the KEGG database revealed the significant participation of detected proteins in pathogenic E. coli infection (ACTG1, TUBA1C, TUBA4A, TUBB, TUBB8, and YWHAZ), which may indicate microbiota changes associated with being in space." (PMID 31547269, 2019).
glaucoma (2 papers, 2018 to 2021). Increased pressure in the eyeball due to obstruction of the outflow of aqueous humor. "These proteins included the 14-3-3 protein epsilon (YWHAE) and 14-3-3 protein zeta/delta (YWHAZ), which belong to the same protein family and YWHAZ has been previously found to be upregulated in the tears of patients using topical anti-glaucoma medication." (PMID 30104599, 2018).
osteoporosis (2 papers, 2017 to 2022). A condition of reduced bone mass, with decreased cortical thickness and a decrease in the number and size of the trabeculae of cancellous bone (but normal chemical composition), resulting in increased fracture incidence. "Based on our data we recommend testing of B2M, GAPDH, RPL19, and YWHAZ for relative quantification of gene expression studies in ovine bone which it is a robust bio-medical model for evaluating bone-substituents in osteoporosis." (PMID 29258442, 2017). "Despite OVX with deficient diet, glucocorticoid proved to be the most suitable osteoporosis model in sheep, and it was recommended to test B2M, GAPDH, RPL19, and YWHAZ gene expression that represented standard reference genes for a relative quantification of transcriptional activity of ovine bone." (PMID 36012173, 2022).
sarcoma (2 papers, 2016 to 2018). A usually aggressive malignant neoplasm of the soft tissue or bone. "(3B) In CSC and native cells from sarcoma, the NormFinder software identified GAPDH, YWHAZ and 18S rRNA as the most stable genes, instead G6PD, RPL13a and B2M were the less stable." (PMID 26894994, 2016). "The most stable HKG for the CSC and native cells obtained only from sarcoma were GAPDH and YWHAZ, whereas for carcinoma we identified PPIA, HMBS or RPL13a." (PMID 26894994, 2016). "Notably, YWHAZ and GAPDH were revealed as the most stable HKG in all the pH conditions, confirming its suitability as a HKG to gene normalization of sarcoma cells." (PMID 30261649, 2018). "We analyzed the expression of the stemness genes c-Myc, KLF4, Nanog, and OCT3/4 that were previously normalized to ACTB, with the identified top-ranking HKG for CSC and native cells, in sarcoma and carcinoma, respectively (GAPDH and YWHAZ for sarcoma, and PPIA and HMBS for carcinoma)." (PMID 26894994, 2016).
urothelial carcinomas of the urinary bladder (2 papers, 2019 to 2022). "The objective of this study was to characterize the oncogenic actions of a recently identified cancer‐associated gene YWHAZ (also named as 14‐3‐3 ζ/δ) in urothelial carcinomas of the urinary bladder (UCUB)." (PMID 30945298, 2019).
uveal melanoma (2 papers, 2014 to 2020). A melanoma derived from melanocytes of the uveal tract. "Several genes, such as HTR2B, CHL1, the ZNF family, YWHAZ and FYN provide potential candidates for distinguishing between uveal melanoma whether contain liver metastases in the future." (PMID 24597767, 2014). "YWHAZ and FYN were identified as key genes in uveal melanoma liver metastases and play crucial roles in cell proliferation, which may be related to the higher incidence of metastases in uveal melanoma." (PMID 24597767, 2014).
acute pancreatitis (1 paper, 2016). An acute inflammatory process that leads to necrosis of the pancreatic parenchyma. "Due to the unavoidable degradation of RNA by enzymes in pancreatic tissue during acute pancreatitis, YWHAZ should serve as a suitable reference gene." (PMID 27069927, 2016). "Thus, we recommend the use of RPL-13A or a combination of RPL-13A and YWHAZ for normalization in qRT-PCR analyses of gene expression in mouse models of acute pancreatitis." (PMID 27069927, 2016).
attention deficit-hyperactivity disorder (1 paper, 2014). A disorder characterized by a marked pattern of inattention and/or hyperactivity-impulsivity that is inconsistent with developmental level and clearly interferes with functioning in at least two settings (e.g. at home and at school). "YWHAZ is cocited with FZD7 in a paper on attention-deficit/hyperactivity disorder, with ATXN1 in a paper on the interaction of Akt-Phosphorylated Ataxin-1 with 14-3-3, and with SOS2 in a paper on epidermal growth factor receptor phosphorylation sites." (PMID 25148247, 2014).
autism spectrum disorder (1 paper, 2020). A spectrum of developmental disorders that includes autism, and Asperger syndrome. "We previously pinpointed YWHAZ (encoding 14-3-3ζ) as a candidate gene for autism spectrum disorder (ASD) through a whole-exome sequencing study, which identified a frameshift variant within the gene (c.659-660insT, p.L220Ffs*18)." (PMID 32545830, 2020).
Cerebral ischemia (1 paper, 2010). Restriction of arterial blood supply to the brain associated with insufficient oxygenation to support the metabolic requirements of the tissue. "In this study we demonstrate that EF1α, RPL13a and YWHAZ are suitable genes for the RT-qPCR analysis and comparison of several sources of human MSC during in vitro characterization and differentiation as well as in an ex vivo animal model of global cerebral ischemia." (PMID 20716364, 2010).
cholesteatoma (1 paper, 2020). A pathologic process characterized by the proliferation of keratinizing squamous epithelium resulting in the accumulation of keratin and cells in the middle ear and/or mastoid. "However, the differences in expression levels between tissue groups for each gene were small; only the expression of HPRT1, PGK1, PPIA, ATP5B and YWHAZ was significantly higher in healthy MA compared to the mucosa from the middle ear in cholesteatoma patients." (PMID 32915926, 2020).
Cirrhosis (1 paper, 2013). A chronic disorder of the liver in which liver tissue becomes scarred and is partially replaced by regenerative nodules and fibrotic tissue resulting in loss of liver function. "Interestingly, three cancer-mutated genes had a similar differential co-expression pattern with YWHAZ, and all have a sharp correlation collapse in cirrhosis (cluster I)." (PMID 24564909, 2013).
developmental delays (1 paper, 2024). "Similarly, YWHAZ deficiency in animals results in developmental delays, increased inflammation, and musculoskeletal deficits." (PMID 38674334, 2024).
diabetic nephropathy (1 paper, 2021). "In non-cancerous renal tissue, suppression of YWHAZ gene expression has resulted in glomerular mesangial cell proliferation in early diabetic nephropathy in primary mouse mesangial cells." (PMID 34882702, 2021).
dry eye (1 paper, 2022). "Additionally, the expression of both YWHAZ and HSPA8 has been shown to negatively correlate with fluorescein tear break-up time (FTBUT), suggesting these proteins may play a role in dry eye symptoms." (PMID 35216421, 2022).
dyslipidemia (1 paper, 2021). "We previously showed that disorders of the mouse sperm capacitation process could be associated with decreased sperm YWHAZ content in a pathological situation such as dyslipidemia." (PMID 34576131, 2021).
endometrial cancer (1 paper, 2021). Primary or metastatic malignant neoplasm involving the endometrium (mucous membrane that lines the endometrial cavity). "These are ERRFI1, IL6, PIK3R1 and SPRY2 which were found to be upregulated and YWHAZ which was found to be downregulated; Endometrial cancer has twelve genes." (PMID 34764329, 2021).
gestational diabetes mellitus (1 paper, 2020). "One research reported that YWHAZ mRNA and protein levels are significantly upregulated in the placental tissues of gestational diabetes mellitus (GDM) patients due to the downregulation of miR-214." (PMID 32851081, 2020).
glomerular diseases (1 paper, 2016). "We checked the most important 4 genes YWHAZ, ACTB, APC, and FYN in differentially regulated genes list and found that they were all regulated in at least 3 glomerular diseases, especially the APC was regulated in all 5 glomerular diseases." (PMID 27227331, 2016).
gout (1 paper, 2022). A condition characterized by painful swelling of the joints, which is caused by deposition of urate crystals. "Mandenol, the corn silk compound, had high activity when docking with the target YWHAG and good activity when docking with the CTNNB1 and YWHAZ targets, suggesting that Mandenol may be an essential corn silk compound for gout." (PMID 36276864, 2022). "The main corn silk compound, Mandenol, treated gout by targeting the Hippo signaling pathway through the CTNNB1, YWHAG, and YWHAZ proteins." (PMID 36276864, 2022). "Our PPI analysis showed that turmeric and corn silk influence gout through their impact on a complex biological network, including HSPA1B, HSP90AB1, STUB1, CTNNB1, YWHAG, and YWHAZ." (PMID 36276864, 2022). "The essential compound of corn silk is mandenol, which may target the hippo signaling pathway to treat gout through CTNNB1, YWHAG, and YWHAZ proteins." (PMID 36276864, 2022).
Hypertension (1 paper, 2021). The presence of chronic increased pressure in the systemic arterial system. "To validate results from available databases, we examined the expression of YWHAZ and SLC4A1AP, the best candidate RGs, in FFPE-derived specimens from patients with hypertension (HT, n = 11) and non-diseased controls (NDC, n = 5)." (PMID 34882702, 2021).
hypertensive nephropathy (1 paper, 2021). Kidney damage that results from chronically elevated blood pressure; complications include glomerular damage resulting in proteinuria and hematuria. "Expression variability of 4 candidate genes (YWHAZ, SLC4A1AP, RPS13 and ACTB) was further examined by qPCR in biopsies from patients with hypertensive nephropathy (n = 11) and healthy controls (n = 5)." (PMID 34882702, 2021).
intrauterine growth restriction (1 paper, 2025). "Dysregulation of the miR-30c-5p/YWHAZ axis has been linked to vascular and inflammatory disturbances in intrauterine growth restriction (IUGR) and pre-eclampsia suggesting that reduced YWHAZ may similarly reflect altered placental signaling in aneuploid pregnancies." (PMID 41614738, 2025).
ischemia (1 paper, 2010). A hypoperfusion of the BLOOD through an organ or tissue caused by a PATHOLOGIC CONSTRICTION or obstruction of its BLOOD VESSELS, or an absence of BLOOD CIRCULATION. "In addition, species-specific primer pairs for human RPL13a and YWHAZ as well as rat RPL13a were found to be suitable for RT-qPCR analysis in the cross-species scenario of human MIAMI cells injected into a rat hippocampal organotypic model of ischemia." (PMID 20716364, 2010).
lung fibrosis (1 paper, 2023). "In the context of pulmonary fibrosis, YWHAZ can regulate genes involved in various types of signal transmission." (PMID 37888708, 2023). "Our combined PCR array–omics analysis demonstrated that DEPs can induce airway inflammation and lead to lung fibrosis through changes in the expression levels of YWHAZ, β-catenin, vimentin, and TGF-β." (PMID 37888708, 2023). "Notably, we found that DEPs induced fibrosis-related changes, along with increases in the levels of collagen, β-catenin, vimentin, and TGF-β; these findings suggest the involvement of endogenous Wnt/β-catenin and YWHAZ-induced vimentin in pulmonary fibrosis pathways." (PMID 37888708, 2023). "Mechanistic analyses showed that the vimentin and TGF-β levels increased due to interactions among YWHAZ, β-catenin, vimentin, and TGF-β, all of which are involved in the induction of lung fibrosis." (PMID 37888708, 2023).
lymph node metastases (1 paper, 2019). "In analysis of TCGA-PRAD data from 333 primary PCs, increased YWHAZ transcript correlated with Gleason grade in a highly-significant manner, and was higher in patients with lymph node metastases, biochemical recurrence and in non-organ-confined disease." (PMID 31043708, 2019).
neuroblastoma (1 paper, 2010). Neuroblastoma (NB) is the most common solid, extracranial childhood tumor. "For 34 neuroblastoma samples, the proposed new algorithm yielded the smallest upper bound for the variance of the geometric mean of six genes, ACTB, B2M, GAPDH, HPRT1, TBP, and YWHAZ." (PMID 20470420, 2010).
nonalcoholic steatohepatitis (1 paper, 2020). "Additionally, in the nonalcoholic steatohepatitis (NASH) model, the YWHAZ and ACTB genes were found to be the most stable and the CYC1 and B2M genes were the least stable." (PMID 32089674, 2020).
oral cancer (1 paper, 2023). "LUCAT1 promotes cell invasion in several cancer types, including gastric, liver, and oral cancer cells, by modulating YWHAZ, Annexin A2, or PCNA." (PMID 36980216, 2023).
pulmonary TB (1 paper, 2025). "To identify the most stable HKGs for analyzing material from patients with pulmonary TB, we selected eight genes—ACTB, B2M, GAPDH, HPRT1, PPIA, RPL13A, YWHAZ and UBC—that are most commonly employed as reference genes in clinical studies." (PMID 41303702, 2025). "Our findings endorse a three-gene panel (PPIA, YWHAZ, HPRT1) for robust normalization of host gene-expression studies in both lesion tissue and PBMCs in pulmonary TB and highlight the necessity of context-specific reference-gene validation." (PMID 41303702, 2025).
RASopathy (1 paper, 2023). Developmental syndromes caused by germline mutations (or in rare cases by somatic mosaicism) in genes that alter the Ras subfamily and mitogen-activated protein kinases that control signal transduction. "Multigene panel for common RASopathy genes that includes BRAF, MAP2K1, MAP2K2, KRAS and YWHAZ usually detects up to 90% of individuals with CFC and it is the preferred initial test." (PMID 38136934, 2023).
renal fibrosis (1 paper, 2020). A final common manifestation of a wide variety of chronic kidney diseases characterized by glomerulosclerosis and tubulointerstitial fibrosis. "Mir-181a-5p has been found to downregulate lipid metabolism regulator PPARα and is in silico predicted to downregulate MAT2A, TIMP3, and LGSF11; miR-451 downregulates YWHAZ and CAB39, which could be implicated in renal fibrosis and mesangial hypertrophy." (PMID 32849923, 2020).
rheumatoid arthritis (1 paper, 2025). A chronic, systemic autoimmune disorder characterized by inflammation in the synovial membranes and articular surfaces. "While YWHAZ promotes inflammation resolution in rheumatoid arthritis via regulatory T cells and M2 macrophages, our data show patient uEVs induce robust NF-κB activation comparable with TNF-α, suggesting context-dependent pro-inflammatory effects in refractory IC/BPS." (PMID 41516009, 2025).
thyroid carcinoma (1 paper, 2025). "Based on the TIMER platform, PIK3R1 has the strongest association with thyroid carcinoma, and notably, YWHAZ also correlated strongly with thyroid carcinoma in immune cell infiltration." (PMID 39403688, 2025).
type 2 diabetes (1 paper, 2022). "Expression of YWHAZ mRNA in β cells and islets from cadaveric donor islets with type 2 diabetes is increased when compared with healthy donor islets." (PMID 35298439, 2022).
urothelial carcinoma (1 paper, 2023). A malignant neoplasm derived from the transitional epithelium of the urinary tract (urinary bladder, ureter, urethra, or renal pelvis). "Tyrosine 3-monooxygenase/tryptophan 5-monooxygenase activation protein zeta (YWHAZ/14-3-3ζ) is an oncogene overexpressed in multiple cancers, such as HCC, CRC, LUAD, BC, and urothelial carcinomas." (PMID 37834160, 2023).